NF1 (neurofibromin 1)
Diseases named in the same sentence as NF1 in open-access papers (continued):
Sharing a sentence is not in itself a finding about the gene and the disease.
tumor (continued). "In our analysis, RECQL4 expression showed divergent patterns across tumor types, being upregulated in HGG but reduced in MPNST, particularly NF1-associated cases, suggesting that its biological role and potential as a therapeutic target may be context-dependent." (PMID 41317405, 2025). "Interestingly, NF1 mutations are often absent in the primary tumor but emerge during metastatic progression or in advanced BC." (PMID 41155378, 2025). "Moreover, NF1 WT human Schwann cells are not sensitive to this combination, suggesting the NF1 loss tumor cells are uniquely responsive to simultaneous targeting of RAF dimerization and MEK, and the central role of ERK signaling in driving NF1-MPNST." (PMID 41023593, 2025). "Although these technologies have not yet been directly applied to NF1, they represent important methodological breakthroughs that could conceptually enhance variant classification, tumor stratification, and personalized care for this disorder." (PMID 40428382, 2025). "Furthermore, a defined subset of CpG islands successfully distinguished circulating DNA from MPNST patients from that of non-malignant NF1 cases, indicating that tumour-associated hypermethylation patterns are also reflected in the bloodstream." (PMID 40843672, 2025). "These gene expression profiles provide valuable insights into whether a tumor may be linked to NF1, even in cases where clinical symptoms have not yet fully developed." (PMID 40428382, 2025). "However, little activity was observed in the NF1-LOF tumor cell lines, MeWo and NCI-H1838." (PMID 40111124, 2025). "However, these patients still need regular neuroradiological and ophthalmological monitoring, with intervals determined by factors such as tumor location, symptoms, and the presence or absence of NF–1 association." (PMID 40867225, 2025). "Loss-of-function mutations in NF1 lead to sustained RAS activation, triggering dysregulated downstream signaling primarily through the MAPK/ERK pathway, which drives abnormal cell proliferation and tumorigenesis, contributing to the development of NF1-associated neoplasms." (PMID 40271285, 2025). "While the duodenal MM was initially considered a metastasis from the ocular lesion, the possibility that it was a de novo tumor arising from the NF1 mutation could not be excluded." (PMID 41001300, 2025). "However, when neurofibromin is absent or non-functional due to NF1 gene mutations, Ras signaling becomes overactive, leading to uncontrolled cell proliferation and tumor formation." (PMID 40428382, 2025). "NF1 gene is a known tumour suppressor gene and fusion events may lead to gene inactivation." (PMID 39789097, 2025). "Unlike personalized tumor-informed assays that require patient-specific sequencing, our panel-based approach offers a scalable, off-the-shelf method for high-depth ctDNA profiling in NF1-associated MPNST." (PMID 41255978, 2025). "Notably, in NF1-related MPNSTs, the loss of CDKN2A may act synergistically with epigenetic silencing and mechanical restructuring at the cellular level, enhancing tumor heterogeneity and drug resistance." (PMID 40630199, 2025). "Also, the neurofibromin protein NF1 as a tumor suppressor was monitored." (PMID 38565978, 2024). "NF1 is a tumor suppressor gene and encodes neurofibromin, a negative regulator of RAS proteins." (PMID 39176108, 2024). "All nine patients presenting with a constitutional gene mutation (e.g., MEN1 and NF1) were alieved at the 10 year follow-up period, showing a good outcome, while the OS was not different (p = 0.75) in 19 patients with concomitant neoplasia as compared to 52 without." (PMID 39001434, 2024). "In normal conditions, neurofibromin binds RAS to regulate RAF-MEK-ERK activation of the MAPK pathway; however, mutations in the Nf1 gene result in reduced or absent neurofibromin activity in individuals with NF1, causing uncontrolled cell growth and tumor formation." (PMID 38804352, 2024).
tumor (continued). "Interestingly, NF1-associated pNFs and MPNSTs also express CD271, suggesting a mechanism wherein stem-like properties may contribute to tumor progression." (PMID 39518076, 2024). "Furthermore, the early clinical and biomarker evidence suggests that NFX 179 Topical Gel may have therapeutic potential in treating NF1 by reducing cNF tumor volume." (PMID 38691597, 2024). "In this review, we explore the current state of the field and critical knowledge gaps regarding the role of NF1(Nf1) haploinsufficiency on immune cell function, as well as the putative impact of Schwann cell lineage states on immune cell recruitment and function within the tumor field." (PMID 38473354, 2024). "Although the MAX mutation is classified as type C2, including RET, NF1, TMEM127,H-RAS and ATRX, which belongs to the SWI/SNF family of chromatin remodeling proteins, as their upregulation will activate the PI3K/AKT and RAS/MAPK signaling pathways resulting in tumor formation." (PMID 39279998, 2024). "In addition to BRAF, the second most common mutation in MAPK pathway is the small GTPase NRAS (25%), and the third is the tumour suppressor and the negative regulator of RAS, neurofibromin 1 (NF1) (14%); both these mutations lead to the activation of the MAPK pathway and increased ERK signalling." (PMID 36967556, 2023). "Mutations in Nf1 and Ink4a/Arf are commonly found in ERMS tumors (15% and 4%, respectively), and this genetic combination follows the familiar pattern of Ras-pathway mutation coupled with the loss of a tumor suppressor that is found in other commonly-used RMS models." (PMID 36826025, 2023). "Many of the most frequent actionable alterations within TMB-H tumors were within tumor suppressor pathways (PIK3CA/PTEN, CDKN2A, BRCA1/2, NF1, ATM, and TSC1/2), suggesting that many variants may be passenger rather than driver alterations in the setting of highly altered tumors." (PMID 36602798, 2023). "The site of PPGL tumours may also vary according to the genetic cause, for example SDH mutations may be associated with tumours in the adrenal, abdomen or head and neck, while RET- and NF1-related tumours are usually located in the adrenal rather than other locations." (PMID 37761307, 2023). "In contrast, NF1 is a relative benign tumor type that may have minimal impact on the GI functions." (PMID 36755948, 2023). "Notably, knockdown of NF1 led to a marked inhibition of tumor growth." (PMID 37147639, 2023). "Selective MEK1/2 inhibition may inhibit tumor growth in patients with tumors caused by RAS dysregulation; MEK1/2 are therefore potential actionable therapeutic targets for tumors occurring in patients with NF1." (PMID 37400844, 2023). "Consequently, patients with NF1 are born with one mutated copy of the NF1 gene, and tumors develop after acquired loss of the remaining NF1 in the tumor without any other recurrent oncogenic alterations." (PMID 37959175, 2023). "However, when compared to another MEK inhibitor, selumetinib (AZD6244, ARRY-142886), which was recently approved to treat children’s NF-1-related symptomatic, inoperable pNFs, the capacity of tumor amelioration is barely satisfactory with the ORR of 44.2% versus 73.8%." (PMID 36015104, 2022). "Moreover, we identified one somatic NF1 mutation not observed in tumor tissue, suggesting polyclonal evolution in this patient." (PMID 35965534, 2022). "Mutations in the NF1 gene may lead to dysregulation of the RAS-RAF-MEK-ERK signaling pathway, which may cause cells to grow, divide, and replicate in an uncontrolled manner, and may lead to tumor growth." (PMID 35865459, 2022).
tumor (continued). "Mesenchymal transition from another subtype is associated with highly elevated levels of tumor-associated macrophages (TAMs) and tumor-infiltrating T cells; the upregulation of the NF-κB pathway via increased TNF-α (tumor necrosis factor-α) signaling in the TME; and deactivation of NF1." (PMID 35690784, 2022). "Importantly, both of these tumor types have a much higher rate of germline NF1 alterations." (PMID 36008825, 2022). "To date, although targeted MEK inhibition has been the most effective avenue in eliciting tumor reduction responses, the success is not universal for all NF1-associated tumors, and the long-term efficacy of this treatment remains unknown." (PMID 35188187, 2022). "Culturing pheochromocytomas from animal tumours led to the development of the rat PC12 cell line, which carries a Max gene variant, and the MPC and derived MTT mouse cell lines that originated from the Nf1 knockout mouse, as well as the more recent RS0 cell line from rats lacking SDHB." (PMID 36178902, 2022). "Moreover, as the majority of patients with NF1 develop non-tumor-related comorbidities (e.g. cognitive deficits), a subset of which are not dependent on RAS-MEK activity, the identification of RAS-independent targetable proteins or pathways will be critical for their management." (PMID 35188187, 2022). "In addition, recent genotype–phenotype correlations studies suggest that NF1 may be more relevant in tumor initiation and progression than previously thought." (PMID 36009591, 2022). "One NF1 somatic mutation not detected by tumor sequencing was identified with plasma WES." (PMID 35965534, 2022). "Shared biallelic NF1 inactivation was present in all three tumor pairs, as well as shared CDKN2A homozygous deletion and ATRX mutation in two tumor pairs each, thereby indicating these were initiating truncal events critical to gliomagenesis in the setting of NF1." (PMID 35945463, 2022). "Therefore, the majority of NF1 related tumor researches could be categorized into benign tumor studies or malignant tumor studies." (PMID 33630851, 2021). "Besides NF1-related neoplasms, they also affect sporadic or de novo tumors." (PMID 34566848, 2021). "As the patients to this study were collected because of a wider spectrum of NF1-like syndromes and features, and consequently underwent NF1’s genetic testing, the cohort and our results could have a bias of more and mostly pediatric tumor related NF1-like syndromes." (PMID 34325699, 2021). "In addition, the miniMg-∆MEF3/NF1-HSV promoter effectively targeted tumour cells and lowered chemotherapy dose, and so could be employed in combination with a chemotherapeutic regime." (PMID 32973362, 2021). "To investigate whether tumour cells were present after the 8 day treatment protocol that could still respond to GCV, we assayed HSV-TK expression, which was significantly increased in LV-miniMg-∆MEF3/NF1-HSV tumour samples compared with LV-∆miniMg-HSV controls." (PMID 32973362, 2021). "However, in just one of these cases was assumed a sporadic mutation for NF1 gene and the inheritance of other condition, and in only two cases this association was related with tumor formation, but none of them with optic gliomas." (PMID 32533764, 2020). "The functional loss of neurofibromin caused by NF1 mutations will lead to sustained activation of intracellular RAS-GTP and prolonged activation of the RAS/RAF/MAPK signaling pathway, which eventually results in increased cellular proliferation and even uncontrollable tumor growth." (PMID 33061844, 2020). "Therefore, NF1 has been identified as a tumor-provoking condition." (PMID 32399324, 2020).
tumor (continued). "Additionally, NF1 mutation status was significantly predicted by contrast-enhancing volume and tumor bulk volume, whereas PDGFR-α was significantly predicted by T2-FLAIR hyperintensity/total tumor volume and tumor bulk/total tumor volume ratios." (PMID 31795520, 2019). "Besides the biallelic NF1 gene inactivation necessary for tumor development, it is currently known that further molecular alterations, such as epigenetic changes (often involving miRNAs), may promote uncontrolled tumor growth." (PMID 31694342, 2019). "Moreover, it is not yet known if biallelic or monoallelic loss of NF1 contributes to tumor progression in sporadic cancers." (PMID 31199580, 2019). "Interestingly, another tumor suppressor, NF1 protein, which regulates Ras activity, has been shown to associate with K14 in the basal epidermal layer during development in skin, suggesting that K14 may regulate the function of this tumor suppressor." (PMID 31126068, 2019). "Mutations in NF1, TSC2 or PTEN-encoding for key suppressor genes of this pathway, and altered expression of the mTOR pathway components, are common hallmarks of a great proportion of NETs, wherein these alterations seem to be directly related with tumour development and progression." (PMID 31443481, 2019). "Altogether, we propose that the enhanced function of some NF1+/− immune cells in the tumor microenvironment of NF1 patients may favor the benign tumor state (i.e. NF1+/− mast cells, macrophages), but can also impair malignant transformation (i.e. NF1+/− T cells)." (PMID 30479396, 2018). "The five TLR proteins were identified in tumor cells, in both GBM cell lineages with mutational status consistent for the mesenchymal subtype (U87MG and A172): RB transcriptional corepressor (RB1) missense mutation in A172, and neurofibromin (NF1) missense and deletion mutation in U87MG." (PMID 29912993, 2018). "Tumor blocks were not available for further analysis and it is unknown if the NF1 mutation was sub-clonal in the primary tumor." (PMID 30345349, 2018). "While MEK inhibition may be demonstrated to be a successful therapeutic approach for cNF, the development of new cNF trials is partially dependent on the identification of novel and pharmacologically tractable molecular targets with critical relevance to NF1 tumour biology." (PMID 29695767, 2018). "Importantly, and in agreement with the virtual absence of phenotypes from keratinocytes of NF1 patients, Nf1+/− murine keratinocytes do not spontaneously transform into a tumor in vivo unless additional mutational events are induced." (PMID 30479396, 2018). "Most of the detected alterations were unique to one tumor, but some genes harbored non-silent somatic mutations in two or more samples, including the NF1 gene as could be expected." (PMID 29159601, 2018). "Thus, Nf1+/− macrophages in the tumor microenvironment have an established pro-tumorigenesis role and interfering with macrophage function may be of therapeutic interest for NF1 patients." (PMID 30479396, 2018). "This confirms the previously reported CD74-NRG1 fusion and also suggests that the NRG1, NF1 and Hippo pathway fusions may play important roles in tumours without known driver mutations and that this prognostic factor may be associated with poor survival." (PMID 28637487, 2017). "While our study did not meet final accrual and was not powered to detect differences in response rates between sporadic and NF1-associated MPNST, this chemotherapy regimen used resulted in disease stabilization in a majority of the patients, which is important in a highly aggressive tumor." (PMID 29138631, 2017).
tumor (continued). "Thus, the analysis of COPRS expression should be performed using primary MPNST samples(with high proportions of tumour cells) from patients with NF1 microdeletions to explore the role of COPRS during MPNST development or progression inNF1 microdeletion patients." (PMID 28213670, 2017). "CNAs dominate the breast cancer genome, with NF1 gene amplification being a particular feature not seen in the other tumour types in which NF1 mutations are observed, suggesting that gain of neurofibromin function is especially important in breast cancer biology." (PMID 28637487, 2017). "Hence, the NF1 gene has a potential role as a tumor suppressor gene." (PMID 26604930, 2015). "Concerning whole-body imaging, assessment of not just the mere anatomical tumor load but of the metabolically active portion of tumors may provide more useful information concerning NF1 biology, the risk of malignancy or correlation with serum markers." (PMID 26625155, 2015). "By applying the same ‘exclusivity analysis’ to mutation data from other tumor types, however, we identified or confirmed other pairs of mutations—mutant KRAS and BRAF in COAD, mutant EGFR and NF1 in GBM, and mutant BRAF and NRAS in SKCM —that may be synthetically lethal in those tumors." (PMID 26047463, 2015). "However, LOH at the NF1 locus was also found in PNs, suggesting that other genetic and/or epigenetic alterations may be involved in tumor progression in NF1." (PMID 25109740, 2014). "However, the emerging recognition of the role of NF1 in sporadic cancers may lead to the development of NF1-based treatments for other tumour types." (PMID 25026295, 2014). "However it is unknown if the same mutation exists in NF-1 patients with co-existent GISTs and GEP NE tumours, and more importantly, it is unknown if there are such mutations in non-NF-1 patients with co-existent GISTs and GEP NE tumours." (PMID 19216788, 2009). "Three of these cases also exhibited concurrent alterations in the tumour suppressor genes ARID1A, NF1, or RB1, suggesting even poorer prognosis and a need for more intensive follow‐up or more aggressive interventions beyond EGFR TKI monotherapy." (PMID 41015991, 2025). "Overall, the combination of LXH254 plus trametinib demonstrated overall better anti-tumor activity in our four xenograft models of NF1-MPNST through greater inhibition in ERK and cell cycle signaling, and subsequent reduction in tumor proliferation." (PMID 41023593, 2025). "AI-HOPE-RTK-RAS also supported the exploration of sex, tumor location, and survival outcomes in KRAS- and NF1-mutant contexts." (PMID 40868090, 2025). "They showed that NF1, TSC1, and TGF-β RII are important tumour suppressors that regulate immune composition, and their loss enhances IL6-JAK3-STAT3/6 inflammatory pathways, increasing LAG3 + CD8 and CD4 T cells." (PMID 40650785, 2025). "The neurofibromin 1 (NF1) protein regulates the downstream RAS/RAF/MEK/ERK pathway and functions as a tumor suppressor." (PMID 41170454, 2025).